RN7SL330P (RNA, 7SL, cytoplasmic 330, pseudogene)
Gene: Miscellaneous RNA gene on chromosome 12 (94,361,220 to 94,361,526, forward strand). Ensembl gene ENSG00000244391.
Homologues: Orthologues: chimpanzee Metazoa_SRP (99% identical), macaque Metazoa_SRP (92% identical). Paralogues in human: RN7SL1 (75% identical), RN7SL3 (75% identical), RN7SL218P (74% identical), RN7SL2 (74% identical), RN7SL45P (74% identical), RN7SL575P (74% identical), RN7SL375P (73% identical), RN7SL414P (73% identical), RN7SL126P (73% identical), RN7SL566P (73% identical), RN7SL203P (73% identical), RN7SL336P (73% identical), and 702 more.